KDM4A (lysine demethylase 4A)
Diseases named in the same sentence as KDM4A in open-access papers (continued):
Sharing a sentence is not in itself a finding about the gene and the disease.
cancer (continued). "The same as KDM4A, KDM4B plays a significant role in cancer." (PMID 29651880, 2018). "Although inhibition of KDM4A has not undergone clinical testing yet in cancer patients it is widely considered an attractive strategy." (PMID 28894274, 2017). "Clinical studies from different groups found that the demethylases of H3K9me2 and me3, such as lysine (K)-specific demethylase 3A (KDM3A, also known as JMJD1A or JHDM2A) and lysine (K)-specific demethylase 4A/B/C (KDM4A/B/C), are highly expressed in cancer tissues and regulate tumorigenesis." (PMID 27034728, 2016). "Identifying what modifications or alterations allow dissociation of KDM4A from the SCF complex will be important and could identify additional pathways that, if misregulated in cancer, could promote TSSGs." (PMID 25995187, 2015). "Thus, blocking the interactions between KDM4A and some other proteins (such as pRb and SP1) may be a therapeutic strategy for some types of cancers." (PMID 29651880, 2018). "Interestingly, while KDM4A and PTK2 have apparently never been considered for gene expression normalization, the consistent expression of EIF4H has been demonstrated in human cancer cells, where it was proposed as a reliable control gene." (PMID 33183298, 2020).
tumor (71 papers, 2011 to 2025). "While both Kdm4a and Sqle loss inhibited tumor organoids growth to varying degrees, with Sqle downregulation having a more pronounced effect, comparable to that of double knockout." (PMID 39461328, 2024). "Different levels of LEF1 and KDM4A enrichment were observed in the promoter regions of the selected genes implicated in tumour suppression or promotion." (PMID 37553362, 2023). "Intriguingly, Kaplan–Meier survival analysis showed that KDM4A proteins in primary HCC tumor tissue were associated with poor overall survival (P < 0.001) of HCC patients in Guilin cohort." (PMID 32883983, 2020). "When we compared the enrichment of the methyl marks present in the intron 1 region to the non-neoplastic cell line MCF10A we found that the presence of KDM4A was associated with a decrease in these epigenetic marks in the tumor cell lines." (PMID 29682202, 2018). "Additionally, apoptosis pathways were upregulated, aligning with the observed growth inhibition and morphological changes in Kdm4a-deficient tumor organoids." (PMID 39461328, 2024). "The epigenetic modifications of KDM4A are also associated with tumor progression." (PMID 37692513, 2023). "The knockout of KDM4A or 4B or 4C reduced neuroblastoma cell proliferation in vitro and tumor growth in vivo." (PMID 40940894, 2025). "In HCC, RFX5 binds to the promoter region of KDM4A to upregulate the expression of KDM4A, thereby inhibiting tumor apoptosis and promoting cell cycle progression." (PMID 39718123, 2025). "In terms of clinical applications, considering the important role of KDM4A in tumor development, small molecule inhibitors targeting KDM4A have been developed." (PMID 39085849, 2024). "In another example, KDM4A is recruited to H3K4me3-rich loci by KDM5A during DNA amplification events in tumours, with similar events occurring during maternal epigenetic inheritance in oocytes." (PMID 39062462, 2024). "A deeper insight into the regulatory roles of KDM4A in NSCLC can help better understand tumor biology and explore new therapeutic strategies." (PMID 39085849, 2024). "Then, treatment with KDM4A inhibitor (QC6352) at a dose of 10 mg/kg alone or in combination with FGL1 mAb was administered to tumor-bearing mice." (PMID 39085849, 2024). "The findings revealed predominant expression of KDM4A in the nucleus, with a significantly elevated expression level in tumor tissues in comparison to normal bladder tissues." (PMID 39461328, 2024). "Cells stably suppressing LEF1 or KDM4A had markedly decreased tumour-initiating capacity, with tumours from the control shRNA (shSCR) group notably larger than those from the other two groups." (PMID 37553362, 2023). "Our results showed that LEF1 recruits KDM4A and N-CoR, functioning in a coordinated manner to transcriptionally inhibit the tumour-suppressor gene LATS2 and promote OSCC progression." (PMID 37553362, 2023). "KDM4A reduces the autoregulation of Sp1 and is negatively correlated with tumor suppressor ARHI expression." (PMID 37692513, 2023). "There are several evidences to suggest that overexpression and activation of KDM4A protein are involved in carcinogenesis and tumor progression, acting as both promoter of oncogenes and negative modulators of onco-suppressor." (PMID 38129913, 2023). "miR-10a functions as a tumor suppressor by negatively modulating the KDM4A-mediated Hippo-YAP1 pathway in PCa." (PMID 37692513, 2023). "In renal carcinoma, KDM4A or KDM6A raises ribosomal protein-coding genes to sustain tumor cell survival under amino acid deprivation." (PMID 37692513, 2023).
tumor (continued). "Compound 41 also exhibited potent anticancer activity and suppressed tumor growth in a tumor-burdened mouse model by modulating KDM4A activity in vivo." (PMID 37692513, 2023). "The combination therapy of KDM4A inhibition and anti-PD-1 antibody suppresses tumor growth mediated by activation of CD8+ T cells." (PMID 35163049, 2022). "H3K9me3 is an important epigenetic mechanism inhibiting gene expression and is mediated by KDM4A to regulate in various tumor cells." (PMID 35287356, 2022). "Of note, KDM4A knockdown or KDM4C knockout in castration-resistant PCa cells also leads to decreased tumor formation." (PMID 35534851, 2022). "Daoke Yang and Yingjuan Zheng at the First Affiliated Hospital of Zhengzhou University, Zhengzhou, China, and co-workers examined KDM4A in human NPC tumor samples and in experiments on mice." (PMID 34385569, 2021). "KDM4A/C/D bind androgen receptor (AR) in vitro and in vivo, resulting in tumor cell proliferation through demethylation of H3K9me3 in AR target genes, stimulating AR-dependent transcription in combination with KDM1A." (PMID 34778065, 2021). "CHD5, a tumor suppressor gene, is under the control of KDM4A, whose silencing restores CHD5 expression by decreasing H3K36me2/me3 histone marks in its locus." (PMID 34778065, 2021). "KDM4A is also directly involved in upregulation of the lung cancer-associated genes CXCL5, ADAM12, and JAG1, involved in angiogenesis promotion, tumor cell growth, and cell proliferation." (PMID 34778065, 2021). "KDM4A protein located in the cell nucleus showed a heterogenous expression pattern in HCC tumor tissues." (PMID 32883983, 2020). "To evaluate the ability of these synthesized compounds to inhibit KDM4A and to modulate methylation levels of lysine 9 and 36, we tested the molecules by in vitro enzymatic assay and in tumor cell lines." (PMID 32523934, 2020). "After they validated KDM4A is directly related to proliferation and xenogaraft tumour growth of BCSC, 34 was tested if it is qualified for the treatment of BCSC-originating tumours." (PMID 29651880, 2018). "The AUC in model 1ofclinical characteristics only, including age, sex, smoking, alcohol drinking, and tumor site, was 0.590 (95% CI = 0.527 to 0.653), which increased to 0.669 (95% CI = 0.609 to 0.730) in model 2, after addition of the KDM4A expression levels." (PMID 29113308, 2017). "Through an analysis of tumor tissues from three cohorts, we found that KDM4A was differently expressed in OSCC tissues with different survival time." (PMID 29113308, 2017). "KDM4A is highly expressed in many tumours where it is also involved in metabolic reprogramming for increased tumour anaerobic glycolysis." (PMID 29100361, 2017). "KDM4A and AR are recruited to cis-regulatory elements of the AR target gene p27kip1, where they inhibit the expression of that tumor suppressor via H3K4me3 demethylation." (PMID 26397136, 2015). "(F) KDM4A mRNA levels in primary tumor tissues of indicated subtypes in GSE25066 cohort." (PMID 40243589, 2025). "The deletion of KDM4A reduced esophageal xenograft tumor growth and metastatic capacity." (PMID 40940894, 2025). "Additionally, in vivo experiments were performed using an HPV11-positive subcutaneous tumor model of SNIP mice to verify the effects of the KDM4A gene knockout." (PMID 41516122, 2025). "Moreover, shRNA-mediated KDM4A knockdown led to a significant reduction in xenograft tumor growth in vivo." (PMID 40940894, 2025). "Furthermore, an analysis was conducted on the immunohistochemical (IHC) staining of KDM4A in tumor tissue of human MIBC and paired normal bladder tissues from six patients." (PMID 39461328, 2024). "Our data show that JNK/c-Jun activation was significantly higher in the control group with normal Kdm4a expression, which may provide a growth advantage for the tumor organoids." (PMID 39461328, 2024).
tumor (continued). "This phenomenon may significantly contribute to the heterogeneous response of different tumor layers to KDM4A-targeted therapies in vivo." (PMID 39461328, 2024). "Interestingly, the results showed that Kdm4a knockout-induced growth inhibition and apoptosis in tumor organoids are highly dependent on Sqle." (PMID 39461328, 2024). "Targeting the upstream regulator KDM4A could simultaneously affect multiple pathways, including cholesterol synthesis, offering a broader inhibition of tumor growth." (PMID 39461328, 2024). "Our results support this hypothesis as Kdm4a knockout reduced ROS levels in tumor cells, and similar ROS clearance could be induced by exogenous SQA supplementation." (PMID 39461328, 2024). "Of note, deregulation of KDM4A isoform has been correlated to carcinogenesis and tumor progression and has been observed in breast, prostate, lung, colon, endometrial and bladder tumours." (PMID 38129913, 2023). "The inhibition of KDM4A activates the formation of liquid-like HP1γ puncta on heterochromatin and causes DNA replication, which promotes intrinsic cGAS-STING signaling in the tumor cells." (PMID 35163049, 2022). "KDM4A inhibition promoted the anti-tumor immune response against squamous cell carcinoma." (PMID 35163049, 2022). "Further exploration into their interactions could reveal the regulatory mechanism of KDM4A in tumor cells." (PMID 35287356, 2022). "KDM4A inhibition activates cGAS-STING signaling in tumor cells." (PMID 34830754, 2021). "To test whether the anti-tumour effect of KDM4A targeting goes beyond changes in cell growth, we also looked to see whether KDM4A knockdown reduced motility or migration in a standard wound healing assay." (PMID 34088988, 2021). "However, despite its involvement in tumor development, proliferation, and aggression, very little is known about this enzyme compared to KDM4A/B." (PMID 34778065, 2021). "However, overexpression of KDM4A in RFX5 depleted cells significantly recovered the tumor growth potential that was compromised by RFX5 knockdown." (PMID 32883983, 2020). "Moreover, by analyzing the correlation between KDM4A staining and clinical and biochemical profiles of patients with HCC, we discovered that tumor size was strongly related to an augmented KDM4A expression (P = 0.047)." (PMID 32883983, 2020). "KDM4A is involved in regulation of apoptosis in tumor cells." (PMID 29383092, 2017). "Last, it has been reported that KDM4A depletion induces apoptosis in tumor cells." (PMID 29383092, 2017). "Loss of KDM4A in hypoxic conditions leads to a decreased HIF-1α mediated transcriptional response and correlates with a reduction in the characteristics associated with tumour aggressiveness, including invasion, migration, and oxygen consumption." (PMID 28894274, 2017). "This suggests that activation of mTORC1 occurs downstream of the PI3K–PDK1–AKT cascade in tumours harbouring IDH1 mutations, supporting the notion that 2HG-mediated inhibition of KDM4A affects the stability of DEPTOR leading to mTOR activation independently of the PI3K/AKT/TSC1-2 pathway." (PMID 27624942, 2016). "Despite the importance of cholesterol for rapid tumor cell proliferation and membrane function, our results revealed that exogenous cholesterol supplementation did not significantly reduce apoptosis caused by Kdm4a knockout." (PMID 39461328, 2024). "Interestingly, KDM4A overexpression results in the (extrachromosomal) amplification of chromosome 1q12, through site-specific re-replication during a single cell cycle, and 1q12 amplification also correlates with KDM4A overexpression in tumor samples." (PMID 35661267, 2022). "Consistently, KDM4A inhibition with the combination of anti-PD-1 antibody treatment suppresses tumor growth and metastasis, suggesting that epigenetic modification of STING signaling mediated by KDM4A histone demethylation might positively drive anti-tumor immunity." (PMID 34830754, 2021).
tumor (continued). "Subsequently, the tumor tissue was extracted, and the expression levels of HPV11E6, HPV11E7, and KDM4A were measured via qRT-PCR." (PMID 41516122, 2025). "Lysine-specific demethylase 4A (KDM4A) is critically involved in epigenetic regulation, tumor development, and response to treatment." (PMID 39085849, 2024). "The results further confirmed that LEF1 and KDM4A were notably upregulated in tumours and that the differential expression of LEF1 and KDM4A was related to OSCC histological grade." (PMID 37553362, 2023). "The expression of the indicated proteins in tumour specimens was analysed by WB, revealing higher LATS2 expression in the LEF1- or KDM4A-knockdown groups." (PMID 37553362, 2023). "We suspect that LEF1 recruits KDM4A/N-CoR and may recruit other epigenetic modification complexes to maintain the homeostasis of histone modifications at target promoters, thereby transcriptionally suppressing tumour-suppressor genes such as LATS2 and inhibiting the progression of OSCC." (PMID 37553362, 2023). "RNA-sequencing (RNA-seq) analysis of 566 samples (44 normal and 522 tumour) suggested that LEF1, KDM4A, and KDM4D were expressed at higher levels in tumour tissues than in normal tissues, whereas KDM4B was expressed at lower levels in tumour tissues." (PMID 37553362, 2023). "The tumour volume of each group was calculated and analysed, demonstrating that LEF1/KDM4A promoted the growth of established tumour xenografts." (PMID 37553362, 2023). "Comparing the expression in the normal epithelium and tumour tissues from histological grade I, II, III, or IV revealed that higher histological grades corresponded to higher LEF1 and KDM4A mRNA expression." (PMID 37553362, 2023). "In parallel, an overall increase in H3K9me2 erasers (KDM3B and KDM4A in basalioma, and KDM3A in the other two tumor types) and a bladder-specific decrease in the reader PRDM6 involved in K9 dimethylation were found." (PMID 37569534, 2023). "KDM4A has also been demonstrated to regulate the PDK-dependent metabolic switch between mitochondrial oxidation and glycolysis in tumor cells." (PMID 36012577, 2022). "KDM4A serves as a coactivator of E2F1 and KDM4B regulates AR signaling and turnover to promote tumor progression." (PMID 35534851, 2022). "Changes in tumor growth and immune phenotypes in response to molecules such as STAT3, KDM4A or heparanase already demonstrate unique responses that depend on their respective activities." (PMID 35069219, 2021). "The mechanism of KDM4A in NPC was evaluated both in vivo and in vitro via RT-qPCR, Western blot analysis, MTT assay, Transwell assay, flow cytometry and tumor formation experiments." (PMID 34385569, 2021). "In vitro, knockdown of KDM4A in MCF-7 cells blocks JUN expression, inhibiting invasion, migration, and tumor formation." (PMID 34778065, 2021). "Also, we found that KDM4A‐KO significantly diminished the effect of PRMT3‐OE on cell apoptosis, γH2AX accumulation and tumor growth." (PMID 41147802, 2025). "To investigate whether the tumor suppressing effect of ML324 depends on the normal function of Kdm4a, we assessed the impact of ML324 (10 μM) on growth of tumor organoids in Kdm4a knockout or control group." (PMID 39461328, 2024). "KDM4A promotes HIF1α expression by inhibiting histone methylation in the HIF1α promoter region, thereby upregulating DDIT4 expression and activating the mTOR signaling pathway to promote tumor proliferation, migration, and invasion." (PMID 36611207, 2023). "Interestingly, RFX5 mRNA has previously been shown overexpressed in HCC compared with non-tumor tissue, which promoted HCC progression via transcriptionally activating KDM4A, TPP1 and YWHAQ." (PMID 37008925, 2023). "We also established NOD/SCID mouse xenograft models using CAL-27 cells to conduct an in vivo analysis of the roles of LEF1 and KDM4A in tumour growth, and our findings show that cells stably suppressing LEF1 or KDM4A have markedly decreased tumour-initiating capacity." (PMID 37553362, 2023).
tumor (continued). "Compared with that of mice in the blank group, tumor growth and weight were enhanced in the mice of the si-NC + OE-DDIT4, OE-KDM4A + PBS or OE-KDM4A + DMSO groups (p < 0.05), and this effect was neutralized by KDM4A silencing or everolimus treatment (p < 0.05)." (PMID 34385569, 2021). "We found that KDM4A was overexpressed in tumor tissue of 42/128 (32.81%) informative HCC cases, but not in non-tumor tissue." (PMID 32883983, 2020). "Compared with adjacent non-tumor tissues, the expression levels of KDM4A were significantly raised in HCC tumor tissues." (PMID 32883983, 2020). "Given the lack of understanding of its role in inflammation, KDM4A also warrants further attention in other inflammatory or immune diseases, as well as tumor immunity." (PMID 29383092, 2017). "Most importantly, our data suggests that should specific KDM4A inhibitors become available they may well have the previously unforeseen benefit of reducing HIF activity and therefore significantly impact tumour aggressiveness and therapy resistance." (PMID 28894274, 2017). "In this study we show that the microRNA hsa-miR-137 (miR137) tumor suppressor regulates expression of an extended network of transcriptional coregulators including KDM1A/LSD1/AOF1, KDM2A/JHDM1A/FBXL11, KDM4A/JMJD2A, KDM5B JARID1B/PLU1, KDM7A/JHDM1D/PHF8, MED1/TRAP220/DRIP205 and NCoA2/SRC2/TIF2." (PMID 26461474, 2015). "The results show that inhibition of KDM4A may be effective on tumour cells that do not respond well to cisplatin, as was observed in specimen MS4 and MS8." (PMID 34088988, 2021). "Additionally, the expression of KDM4A was not related to patient sex, patient age, or tumor histological type (p > 0.05)." (PMID 34385569, 2021). "No genes were found to be recurrently mutated, however, two tumours had mutations in histone methytransferases (SETD2 and KMT2D) and one also had a mutation in a demethylase (KDM4A), all previously associated with neoplasia and all mutations predicted to be deleterious." (PMID 32698852, 2020). "Similarly, KDM4A was overexpressed in ESCC patients who did not respond to anti-PD1 therapy, and application of KDM4 inhibitor (KDM4-IN-4) followed by anti-PD1 therapy led to pronounced suppression of tumor growth in vivo." (PMID 40940894, 2025).